STAT3 (signal transducer and activator of transcription 3)
Diseases named in the same sentence as STAT3 in open-access papers (continued):
Sharing a sentence is not in itself a finding about the gene and the disease.
tumor (continued). "MIFs derived from these CD36+ CAFs activate myeloid‐derived suppressor cells (MDSCs) through the IL‐6/STAT‐3 pathway, promoting an immunosuppressive TME and enhancing tumor stem cell capabilities." (PMID 41164803, 2025). "Co-targeting BET proteins along with key pro-tumor pathways, such as IKBKE or STAT3 signaling, has shown potential to disrupt macrophage polarization and inflammatory signaling simultaneously." (PMID 41583469, 2025). "Various cytokines produced by both tumor and stromal cells, such as GM-CSF, M-CSF, VEGF, IFN-γ, IL-4, IL-6, IL-13, and TGF-β, are involved in MDSC activation through STAT3 pathways." (PMID 40805183, 2025). "To explore the consequences of STAT3 acetylation on its transcriptional activity and its role in tumor progression, we generated MDA-MB-231 cells harboring a mutant form of STAT3 (STAT3K685R), wherein Lys685 of STAT3 was changed to Arg." (PMID 40083697, 2025). "In tumor-associated macrophages (TAMs), YTHDF2 is upregulated via the IL-10/STAT3 pathway and suppresses IFN-γ/STAT1 signaling, maintaining a pro-tumor phenotype." (PMID 41403953, 2025). "Multi-omics profiling of lung adenocarcinoma tumor organoids uncovers SPC-high, alveolar type 2-like cancer cells with enriched STAT3 activity and increased tumorigenic capacity in vivo." (PMID 39930268, 2025). "Western blot analysis of tumor tissues confirmed that fedratinib downregulated key signaling molecules and effector proteins, including JAK2, p-JAK2, STAT3, p-STAT3, vimentin, survivin, and cyclin D1." (PMID 41476794, 2025). "These CAFs activate signaling pathways including RhoA/ROCK, JAK/STAT3, and MAPK, fostering tumor progression." (PMID 41583435, 2025). "Our study provided compelling evidences that the natural compound α-hederin exerts anti-tumor effects by directly targeting USP5, disrupting its interaction with STAT3, and inhibiting STAT3 deubiquitination-a previously unreported mechanism." (PMID 41281755, 2025). "Notably, systemic delivery of an AMPK-stabilizing peptide in tumor-bearing mice preserved adipose tissue mass and mitigated body weight loss without affecting tumor growth, underscoring the therapeutic relevance of modulating AMPK in concert with STAT3 signaling." (PMID 40704145, 2025). "The transcription factor ZEB1 and the STAT3 signaling pathway play crucial roles in EMT, tumor invasion, immune regulation, and chronic inflammatory responses." (PMID 40016707, 2025). "USP5, a deubiquitinating enzyme (DUB) involved in inflammatory responses that is highly expressed in primary CRC tissues and promotes tumorigenesis by stabilizing tumor proteins, was identified in our study as a novel DUB of STAT3." (PMID 41281755, 2025). "What’s more, STAT3 upregulates chemokines like CXCL1 (C-X-C Motif Chemokine Ligand 1) and attracts MDSCs to tumor sites." (PMID 40881676, 2025). "We find that CACS is associated with increased production of IL-6 family members by the tumor, which subsequently accumulate in the serum, leading to activation of the pro-inflammatory JAK/STAT3 pathway in peripheral tissues." (PMID 41278737, 2025). "IL-6 promotes tumor cell proliferation and inhibits apoptosis by activating the Janus kinase (JAK)-signal transducer and activator of transcription 3 (STAT3) pathway, further exacerbating CRC progression." (PMID 40995229, 2025). "By activating the STAT3-cyclinE/CDK2 signaling axis, MSLN accelerates cell cycle progression, thereby promoting tumor cell proliferation." (PMID 41400642, 2025). "HIFA/HIFB proteins drive tumor-promoting growth factors such as VEGF, while STAT3 enhances PD-L1 transcription, facilitating immune evasion by targeting immune cells for apoptosis." (PMID 40649942, 2025). "D2R knockdown inhibits CRC proliferation via the β‐catenin/ZEB1 signaling pathway, while the D2R antagonist domperidone suppresses tumor growth by blocking the MEK/ERK/STAT3 and JAK2/STAT3 signaling pathways." (PMID 41415714, 2025).
tumor (continued). "The IL6-induced JAK/STAT3 signaling pathway elevates the expression of MMP9 in OC cells, degrading the extracellular matrix (ECM) and creating pathways for tumor invasion and metastasis." (PMID 40427188, 2025). "In order to study the tumor progression, including EMT, sustained by upregulation of CD 163 and CD 204 (M2‐TAM) and STAT3, NF‐κB in TME of 100 patients with CC ̧, we analyzed the protein expression of these markers by IH." (PMID 41263059, 2025). "Nearly every immune regulatory mechanism, both cancer cell identification and tumor-driven immune escape, is controlled by the JAK/STAT3 signaling system." (PMID 40487371, 2025). "Further investigation revealed that macrophages upregulate the expression of the long noncoding RNA, Linc01559, in DA through the STAT3/c-MYC signaling pathway, thereby promoting malignant phenotypes such as invasion, metastasis, tumor stemness, and apoptosis." (PMID 40722682, 2025). "Critical signaling pathways, such as STAT3 and PI3K/Akt, play central roles in this polarization process, influencing both tumor growth and immune modulation." (PMID 40136375, 2025). "Combined use of the HDAC3 inhibitor RGFP966 and the BET inhibitor JQ1 was found to significantly suppress GSC proliferation, drive apoptosis, inhibit tumor growth in vivo, and synergistically disrupt the Gli1/IL6/STAT3 axis." (PMID 40450300, 2025). "The AEG-like malignant cells-derived spermine drives macrophage polarization toward Macro_APOE through the activation of STAT3 signaling, thus leading to the establishment of an immunosuppressive TME, ultimately facilitating AEG tumor progression." (PMID 40963562, 2025). "Hypoxia itself promotes cytokine production, and IL-6 can further amplify the hypoxic response via STAT3 and HIF-1α stabilization, forming a detrimental positive feedback loop that exacerbates tumor progression." (PMID 41302515, 2025). "Among these cytokines, IL-10 plays a pro-tumor role through regulating a variety of signaling pathways, including ERK1/2, STAT3 and NF-κB, and regulating the expression of related genes." (PMID 41145470, 2025). "Above all, the treatment of tumor cells with quercetin leads to the inhibition of EMT signaling and, thereby, suppresses the metastasis of tumor cells in vivo by inhibiting the Src/Stat3 signaling pathway." (PMID 41195524, 2025). "In vitro experiments confirmed the regulatory effects of STA on p-STAT3, p-JAK and FN1, indicating that STA can effectively inhibit the expression and function of these genes, thereby exerting anti-tumor effects." (PMID 40772037, 2025). "STAT3, the main effector of JAK signaling, is frequently hyperactivated in GBM, leading to enhanced tumor cell proliferation and resistance to apoptosis." (PMID 40750765, 2025). "The subsequent Western blot analysis of tumor tissues revealed that Lyc.HCL significantly inhibited TRIM22 expression, as well as the expression of JAK2/STAT3 and ERK signaling pathway components." (PMID 40075566, 2025). "Through STAT3 and STAT6 activation, IL-6 stimulates M2 macrophage polarization, tumor growth, and immune suppression." (PMID 41350724, 2025). "Our data suggest that targeting STAT3 will modulate the immunosuppressive TME and enhance anti-tumor immunity." (PMID 40529368, 2025). "Consistent with the tumor inhibitory effect of FZD6 knockdown, the activities of proteins that promote tumor growth including SRC, AKT1, and STAT3 were decreased." (PMID 41286306, 2025). "STAT3 also plays a crucial role in regulating MDSC, promoting their development and proliferation within tumours." (PMID 40407951, 2025). "STAT3 has been reported to be a regulator of the expression of membrane metalloproteases (MMPs), Twist1, and VEGF, which are involved in tumor invasion, migration, and angiogenesis." (PMID 38791608, 2024). "Taken together, these results suggest that GP73 targets the activation of the JAK2/STAT3 pathway to stimulate HUVEC growth and migration in vitro and promotes HCC tumor angiogenesis in vivo." (PMID 38939041, 2024).
tumor (continued). "It has been shown to interact with the JAK/STAT3 and PI3K/AKT signaling pathways as well in tumor cells, which has already been proven in experimental animal models." (PMID 38791932, 2024). "Exosomes released by 4T1 (syngeneic cell lines derived tumor models) cells contain IL-6 and IL-10, which enhance MDSC stimulation and proliferation by promoting STAT3 phosphorylation in myeloid cells." (PMID 38983795, 2024). "This action leads to dimerization and autophosphorylation of the ALK kinase domain and thus abnormally activates downstream signaling pathways, such as PI3K/AKT, JAK/STAT3, and RAS/ERK, finally acquiring tumor-formation activity." (PMID 37940761, 2024). "We further showed that both CpG-Stat3 siRNA and CTLA4 antibody inhibit STAT3 in B malignant cells, leading to tumor cell apoptosis and/or proliferation inhibition." (PMID 39618825, 2024). "Conversely, blocking the IL-6/STAT3 signaling pathway hinders CD44 expression as well as the acquisition of CSC-like characteristics and aggressive tumor behavior." (PMID 39092186, 2024). "LncRNA AB073614 is significantly up-regulated in CRC, resulting in enhanced activation of JAK/STAT3 signaling, a pathway that promotes cancer metastasis and EMT and accelerates tumor progression." (PMID 39030557, 2024). "In our study, nuclear PKM2 acted as a protein kinase, promoting the phosphorylation of STAT3, thereby regulating the expression of downstream glycolysis-related genes such as GLUT1, ENO1, and LDHA, which in turn promotes tumor progression." (PMID 39368995, 2024). "Further, we observed that targeting SIX4 attenuated the transformation of inflammation to cancer in intestinal epithelium via inactivating IL-6/STAT3/SIX4/c-JUN feedback loop, which subsequently suppressed DeltaNp63-mediated tumor stemness signals." (PMID 39309424, 2024). "This is due to high TG2 levels in the tumor’s perinecrotic area which regulate key transcription factors, such as C/EBPb, TAZ, and STAT3, finally promoting GBM growth." (PMID 38474044, 2024). "STAT proteins, especially STAT3 and STAT6, play critical roles in immune-suppression and tumor invasion." (PMID 39525474, 2024). "By inhibiting STAT3, KTN not only reduces the expression of genes that promote metastasis but also enhances the stability and retention of oncolytic viruses within the tumor microenvironment, thereby improving overall therapeutic outcomes." (PMID 39519023, 2024). "The downregulation of ALDOB by STAT3 and GATA2 promotes enhanced glycolytic flux, which is essential for meeting the increased energy demands of rapidly dividing tumor cells." (PMID 39348357, 2024). "In summary, high expression of OASL in tumor tissues activates immune responses such as IFN-γ, STAT1, IL6_JAK_STAT3 signaling, which in turn promotes the expression of PD-L1." (PMID 39286258, 2024). "Tumor stroma-derived LCN2, particularly that secreted by M2 macrophages via STAT3 and C/EBPβ signaling pathways, induces EMT in MCF-7 breast cancer cells, thereby enhancing their migration and invasion capabilities in both in vitro and in vivo models." (PMID 39188682, 2024). "Among these, IL-1B, IL-6, TNF, CXCLs, TGFB1, HMGB1, STAT3, and STAT5 have been reported to contribute to tumor formation." (PMID 39156107, 2024). "Mw is synergistic with therapies that reduce disease burden (e.g. chemotherapy for infection or tumor) and therapies that reduce disease induced immune suppression (e.g. GITR agonist antibody or STAT3 inhibitor)." (PMID 39534596, 2024). "Diosmin was also found to inhibit the activity of the signal transducer and activator of transcription 3 (STAT3) signaling pathway, which is involved in tumor growth and survival." (PMID 39554345, 2024). "IL-28B inhibits the polarization of M2-type macrophages by suppressing the STAT3 and JNK signaling pathways, thereby enhancing the antitumor immune response and delaying tumor progression." (PMID 39867908, 2024).
tumor (continued). "CCL5 binds with a high affinity to the G-protein-coupled receptor, CCR5, which is upstream of multiple pro-tumor signaling pathways including PI3K/Akt and JAK2/STAT3." (PMID 39409924, 2024). "STAT3 is mediator of cytokine signaling within the PDAC TME, and in this capacity, it promotes PDAC tumor cell survival, immune evasion, and proliferation." (PMID 39635662, 2024). "The rationale supporting this approach is based on STAT3 signaling activity that drives resistance through apoptosis, and further evidence that STAT3 inhibition may reverse apoptosis-mediated therapy resistance while re-sensitizing tumor cells to therapeutic agents." (PMID 38339245, 2024). "In both in vivo and in vitro models, the combination of the STAT3 pathway inhibitor WP1066 and radiotherapy significantly delayed tumor progression." (PMID 38605477, 2024). "Inhibit tumor growth; promote tumor apoptosis; the levels of p-SRC, p-EGFR, p-STAT3 and p-AKT are down-regulated." (PMID 39045282, 2024). "Upon activation, phosphorylated STAT3 translocates into the nucleus and promotes the expression of target genes such as cyclin D1, survivin, Bcl-xL, and MCL-1, which are involved in tumor cell proliferation, angiogenesis, and immune evasion." (PMID 39123466, 2024). "Conversely, cGAS–STING-dependent activation of NC-NF-κB signaling can drive IL6/STAT3 signaling and EMT programs, which promote tumor growth and metastasis, respectively." (PMID 39295867, 2024). "We observed that interferon-alpha (IFN-α) and interferon-gamma (IFN-γ) very strongly induced the activation of the STAT1 protein, whereas IL-6 and IFN-α activated STAT3 and IL-4 activated STAT6 in all examined tumor cell lines." (PMID 38396958, 2024). "Delphinidin chloride, a flavonoid compound, can modulate the JAK/STAT3 and MAPK signaling pathways and induce apoptosis in tumor cells." (PMID 39274922, 2024). "In contrast to the tumour promotor activity of miR-221, a recent study unveiled that miR-506-3p involved Janus kinase 2 (JAK2) in controlling the STAT3 activity during doxorubicin chemoresistance." (PMID 39679367, 2024). "Functional inactivation of STAT3 in a subset of PDA cell lines led to significant inhibition in cell proliferation in vitro and reduced tumor growth in vivo." (PMID 38326371, 2024). "Activated STAT3 has been observed in various cancers, including TNBC, where it promoted tumor cell growth, proliferation, anti-apoptosis, migration, and invasion." (PMID 38402166, 2024). "Studies have found that multiple miRNAs in the tumor microenvironment promote the expansion and immunosuppression of MDSCs by targeting inhibiting PTEN and activating the PI3K/AKT/mTOR or STAT3 signaling pathways." (PMID 39206155, 2024). "Piperlongumine, a bioactive alkaloid known for its antioxidant and anti-tumor properties, has been found to inhibit TNBC cell proliferation and migration by inhibiting JAK2/STAT3 pathway phosphorylation." (PMID 38699644, 2024). "The m6A modification of Jak1 mRNA in tumor-infiltrating myeloid cells (TIM) via METTL3 improves the translation efficiency of JAK1 protein and STAT3 phosphorylation." (PMID 39136000, 2024). "Mechanistically, microglia facilitate TME immunosuppression, tumor immune evasion, and tumor MES transition through the mTOR-dependent regulation of STAT3 and NF-κB." (PMID 38891074, 2024). "In our own studies, we have observed that prolactin (PRL) hormone induces STAT3 activation to increase Panc-1 and MiaPaca2 PDAC cell migration and tumor growth." (PMID 38464736, 2024). "In the present study, we also found that methylation of STAT3 by PRMT5/MEP50 in NSCLC cells is important for its transcriptional activity, for the generation and maintenance of CSCs, and for tumour growth in mice." (PMID 38760429, 2024).
tumor (continued). "Colorectal cancer was induced in male BALB/c mice and then was treated with a 30 mg/kg/day oral dose of RA for a week, and it was found to suppress tumor progression in mice through the inhibition of TLR4-mediated NF-κB and STAT3 activation." (PMID 39057035, 2024). "At a dosage of 30 mg/kg, it significantly reduced tumor load and affected PCNA, TUNEL, p-STAT3, and cyclin D1 in vivo." (PMID 38276618, 2024). "Most tumor cells can produce IL-6, which promotes increased PD-L1 expression in neutrophils by activating JAK/STAT3 signal transduction, assisting the tumor in escaping immune surveillance." (PMID 39638788, 2024). "Specifically, the activation of AhR triggers the up-regulation of IL-6, which subsequently mediates signal transducer and activator of transcription 3 (STAT-3) signaling, promoting the expression of IDO-1 in tumor cells." (PMID 39062529, 2024). "Dopamine’s effect on DARPP-32—a tumor-promoting protein—has been shown to increase STAT-3 expression in AGS cells, while in MKN-45 cells, endogenous DARPP-32 actually suppresses STAT-3." (PMID 39767693, 2024). "By downregulating metastasis-related proteins such as MMP-2, STAT3, and IL-8, B7-H3 promotes the motility and invasiveness of tumor cells and through the JAK2/STAT3/MMP-9 signaling pathway." (PMID 38326735, 2024). "We conclude that STAT3 Y640F-mediated inhibition of tumor development and KRAS-induced MEF transformation is dependent on STAT3 phosphorylation at Y705, DNA binding, and gene-specific transactivation." (PMID 38573819, 2024). "Mechanistically, Y-A targets the TNF-α/STAT3 pathway, inhibiting STAT3 and JAK2 phosphorylation, thereby activating apoptotic pathways and suppressing tumor cell growth." (PMID 39056720, 2024). "For example, tumor-derived lactate induces macrophages to convert to M2 by stimulating STAT3 to activate endothelial growth factor (VEGF) and arginine (Arg-1), which further promote tumor development." (PMID 39683818, 2024). "In Gprc5a-ko mice, overexpression of IL-6 reprogrammed the STAT3 pathway and induced recruitment of PMN-MDSCs and polarized macrophages to evade host immunity, leading to metastasis of tumor cells within the mouse lung." (PMID 38609997, 2024). "First of all, STAT3-inducible up-regulation of the myeloid-related protein S100A9 enhances MDSC accumulation, which leads to suppression of anti-tumor immune responses." (PMID 39493763, 2024). "In addition, the release of EVs and IL-6 from colon cancer cells could be mitigated by treating tumor cells with atractylenolide I (an EV biogenesis inhibitor by regulating the STAT3 pathway in tumor cells), and consequently attenuate weight loss in tumor-bearing mice." (PMID 39697630, 2024). "Tumor cells have high expression of VEGF, IL-10, and IL-6; these tumor cells also highly express STAT3." (PMID 38571491, 2024). "Inflammation activates oncogenic signaling pathways including NF-κB, MET, STAT3, mTOR and MAPK, leading to tumor progression and an aggressive phenotype." (PMID 38561856, 2024). "These molecules further drive Treg proliferation and migration through the MAPK/CDK4/6/Rb and STAT3/SIAH2/P27 pathways, reinforcing the immunosuppressive nature of the TME and accelerating tumor progression." (PMID 39493763, 2024). "Significantly higher levels of phosphorylated STAT3, CD206 (a TAM marker in mice) and SIRPα were present in the tumours treated with exosomes with a high ZEB1 level than in those treated with exosomes with a low ZEB1 level." (PMID 38183060, 2024). "Among the few inhibitors targeting the SH2 domain of STAT3 and interacting with STAT5, OPB-31121 has shown anti-tumor activity in leukemia, with ongoing phase I/II clinical trials assessing efficacy against solid tumors and hematopoietic cancers." (PMID 38840908, 2024).